CUTC (cutC copper transporter)
Description:
May play a role in copper homeostasis. Can bind one Cu(1+) per subunit.
Synonyms: CGI-32
Tractability: Small molecule: it has a high-quality binding pocket. PROTAC: ubiquitination databases record sites on it; its protein half-life has been measured.
Gene: Protein-coding gene on chromosome 10 (99,702,558 to 99,756,187, forward strand). Ensembl gene ENSG00000119929.
Subcellular location: Cytoplasm; Nucleus
Subcellular location (Human Protein Atlas): Cytosol; Nucleoplasm; Nucleoli
Pathways (Reactome):
Transport of small molecules: Ion transport by P-type ATPases
Gene Ontology:
Molecular function: copper ion binding; protein binding
Biological process: protein tetramerization; copper ion homeostasis; copper ion transport
Cellular component: cytoplasm; cytosol; nucleolus; nucleoplasm; nucleus
Genetic constraint (gnomAD): Loss-of-function variants: 17 observed, 20.93 expected, observed/expected ratio (o/e) 0.81, 90% interval 0.56 to 1.22. The upper end of that interval is the gene's LOEUF score, 1.22, which puts it in group 5 of 6, group 1 being the genes least tolerant of losing a copy. Missense variants: 226 observed, 239.74 expected, observed/expected ratio (o/e) 0.94, 90% interval 0.85 to 1.05. Synonymous variants: 79 observed, 80.96 expected, observed/expected ratio (o/e) 0.98, 90% interval 0.81 to 1.18.
Homologues: Orthologues: chimpanzee CUTC (100% identical), macaque CUTC (99% identical), pig CUTC (97% identical), dog CUTC (95% identical), rabbit CUTC (94% identical), mouse Cutc (92% identical), guinea pig CUTC (90% identical), rat Cutc (85% identical), tropical clawed frog cutc (74% identical), zebrafish cutc (71% identical), Drosophila melanogaster CG6136 (38% identical), Caenorhabditis elegans cutc-1 (35% identical).
Diseases named in the same sentence as CUTC in open-access papers:
CUTC is named in the same sentence as 15 diseases in open-access papers, as found by Europe PMC text mining. Sharing a sentence is not in itself a finding about the gene and the disease. The quoted sentences say what the papers report.
atherosclerosis (4 papers, 2022 to 2025). A disease characterized by the build-up of fatty material and calcium deposition in the arterial wall resulting in partial or complete occlusion of the arterial lumen. "We speculated that CutC-related bacteria, such as Lachnospiraceae, Muribaculaceae, Clostridium, and Desulfovibrio prompted the progression of atherosclerosis via glycolipid metabolic pathways." (PMID 40098615, 2025). "They concluded that patients with bacteria containing the cutC gene may metabolize choline and promote the development of atherosclerosis." (PMID 37233655, 2023). "Several bacteria taxa (Enterobacteriaceae) had a cutC gene that could convert choline to trimethylamine, which later becomes proatherogenic trimethylamine-N-oxide, which promotes atherosclerosis." (PMID 37233655, 2023).
Obesity (2 papers, 2022). Accumulation of substantial excess body fat. "We then explored the correlation of cntA and cutC with various diseases such as, adenoma, colorectal cancer, impaired glucose tolerance, type 2 diabetes, cardiovascular disease, hypertension, and obesity using several public case-control gut metagenomic datasets." (PMID 35273169, 2022).
Stroke (2 papers, 2024). Sudden impairment of blood flow to a part of the brain due to occlusion or rupture of an artery to the brain. "Recent studies utilizing a mouse model have demonstrated that the gut microbial CutC gene can influence the production of TMA and TMAO, which may subsequently impact stroke severity and result in unfavorable functional outcomes." (PMID 39697484, 2024).
Diarrhea (1 paper, 2024). Abnormally increased frequency (usually defined as three or more) loose or watery bowel movements a day. "Diarrhea with kidney-yang deficiency syndrome increased the activity of CutC in the cecum while having no impact on the small intestine segment." (PMID 38500584, 2024).
renal dysfunction (1 paper, 2022). "Thus, increased plasma TMAO levels in HS fed rats in our study are likely due to a combination of alterations in gut microbiota with increased CutC encoding bacterium and renal dysfunction induced by a HS diet." (PMID 35359866, 2022). "Therefore, alterations in gut microbiota with increased CutC encoding bacterium or renal dysfunction can lead to elevated plasma TMAO levels by promoting TMAO synthesis or reducing TMAO clearance from kidney." (PMID 35359866, 2022).
cardiovascular disease (3 papers, 2022 to 2025). "Due to their broad-host nature, they can be used to target genes present in multiple species throughout the microbiome, such as the cardiovascular disease-associated cutC/cutD genes." (PMID 37389338, 2023). "Choline bioavailability can be diminished by gut microbes that express choline trimethylamine-lyase (cutC), an enzyme that converts choline into trimethylamine (TMA), a precursor for TMA N-oxide (TMAO), which is associated with an increased risk of cardiovascular diseases." (PMID 40852121, 2025).
infection (2 papers, 2017 to 2019). The state of being infected such as from the introduction of a foreign agent such as serum, vaccine, antigenic substance or organism. "BtuB and CutC were also the only genes pertaining to vitamin B12 transport and choline utilization that were identified as candidate infection-specific fitness factors." (PMID 31009518, 2019). "Nine genes of interest were chosen for an initial validation of the Tn-Seq results: 3 mutants were generated to validate candidate fitness factors for in vitro defects (asnA, cvpA, and hflK) and 6 for candidate infection-specific defects (arnA, btuB, cutC, gltB, speA, and tatC)." (PMID 31009518, 2019).
CUTC also shares sentences with these, for which no sentence is quoted: adenoma (1 paper); cerebral infarct (1); colorectal cancer (1); heart disease (1); Hypertension (1); Impaired glucose tolerance (1); tumour (1); type 2 diabetes (1).